CEMIP (cell migration inducing hyaluronidase 1)
Description:
Mediates depolymerization of hyaluronic acid (HA) via the cell membrane-associated clathrin-coated pit endocytic pathway. Binds to hyaluronic acid. Hydrolyzes high molecular weight hyaluronic acid to produce an intermediate-sized product, a process that may occur through rapid vesicle endocytosis and recycling without intracytoplasmic accumulation or digestion in lysosomes. Involved in hyaluronan catabolism in the dermis of the skin and arthritic synovium. Positively regulates epithelial-mesenchymal transition (EMT), and hence tumor cell growth, invasion and cancer dissemination. In collaboration with HSPA5/BIP, promotes cancer cell migration in a calcium and PKC-dependent manner. May be involved in hearing.
Synonyms: HYBID; KIAA1199; IR2155535; TMEM2L; CEMIP1; CCSP1
Tractability: Antibody: its Gene Ontology location is reachable by antibodies, with high confidence; UniProt places it where antibodies can reach, with medium confidence; UniProt predicts a signal peptide or a membrane-spanning region.
Gene: Protein-coding gene on chromosome 15 (80,779,343 to 80,951,776, forward strand). Ensembl gene ENSG00000103888.
Subcellular location: Nucleus; Cytoplasm; Endoplasmic reticulum; Cell membrane; Membrane, clathrin-coated pit; Secreted
Subcellular location (Human Protein Atlas): Nucleoli fibrillar center; Endoplasmic reticulum; Nuclear membrane; Predicted to be secreted
Pathways (Reactome):
Metabolism: Hyaluronan degradation
Gene Ontology:
Molecular function: clathrin heavy chain binding; ER retention sequence binding; hyaluronic acid binding; hyalurononglucosaminidase activity; protein binding
Biological process: hyaluronan catabolic process; positive regulation of cell migration; positive regulation of protein targeting to membrane; positive regulation of release of sequestered calcium ion into cytosol; sensory perception of sound; hyaluronan metabolic process
Cellular component: clathrin-coated endocytic vesicle; cytoplasm; endoplasmic reticulum; fibrillar center; nuclear membrane; plasma membrane; extracellular region; clathrin-coated pit; clathrin-coated vesicle membrane; nucleus
Genetic constraint (gnomAD): Loss-of-function variants: 102 observed, 157.3 expected, observed/expected ratio (o/e) 0.65, 90% interval 0.55 to 0.76. The upper end of that interval is the gene's LOEUF score, 0.76, which puts it in group 3 of 6, group 1 being the genes least tolerant of losing a copy. Missense variants: 1,425 observed, 1,812.3 expected, observed/expected ratio (o/e) 0.79, 90% interval 0.75 to 0.82. Synonymous variants: 666 observed, 678.77 expected, observed/expected ratio (o/e) 0.98, 90% interval 0.92 to 1.05.
Gene-disease validity (ClinGen):
ClinGen rates the evidence that CEMIP causes each of these diseases.
nonsyndromic genetic hearing loss (autosomal recessive): Disputed.
Homologues: Orthologues: chimpanzee CEMIP (99% identical), macaque CEMIP (98% identical), pig CEMIP (91% identical), mouse Cemip (91% identical), rat Cemip (91% identical), dog CEMIP (90% identical), guinea pig CEMIP (90% identical), rabbit CEMIP (89% identical), tropical clawed frog cemip (69% identical), zebrafish cemip (55% identical). Paralogues in human: CEMIP2 (43% identical).
Diseases named in the same sentence as CEMIP in open-access papers:
CEMIP is named in the same sentence as 106 diseases in open-access papers, as found by Europe PMC text mining. Sharing a sentence is not in itself a finding about the gene and the disease. The quoted sentences say what the papers report.
breast carcinoma (45 papers, 2012 to 2025). "TMEM2, transcriptionally activated by SOX4 in breast cancer, functions as a mediator of migratory and invasive processes, suggesting diagnostic potential for CEMIP and TMEM2 quantification." (PMID 40646377, 2025). "Consistently, CEMIP is among one of eight EMT-related genes chosen for a risk assessment model that predicts the risk for metastatic breast cancer to the bone." (PMID 36291875, 2022). "On the other hand, DDIT significantly reduced the expression of hyaluronidases HYAL-2, TMEM2 (encoding the main hyaluronidase expressed in this breast cancer cell line) and KIAA1199/CEMIP, while it enhanced HYAL-1 expression." (PMID 36497283, 2022). "Studies show that high CEMIP expression in primary lung or breast cancer cells is associated with shorter intervals between primary cancer and the metastatic stage, the rapid evolution of brain metastases, and a poor prognosis for the patient." (PMID 35163368, 2022). "Next, we investigated whether an elevated level of CEMIP is associated with increased cell migration in breast cancer cells." (PMID 38838145, 2024). "Recently, it was reported that CEMIP (cell migration-inducing and hyaluronan-binding protein) was associated with migration, invasion and drug resistance in various tumors, particularly in colon cancer, breast cancer, stomach cancer." (PMID 36849460, 2023). "REST knockdown in breast cancer cells leads to the significant upregulation of KIAA1199/CEMIP (cell migration-inducing, hyaluronan-binding protein) and MMP24 (matrix metallopeptidase 24), genes which are involved in cell invasion and metastasis." (PMID 40006989, 2025). "The biological function of CCDC88C in breast cancer metastasis was at least partially mediated by c-JUN-induced CEMIP transcription." (PMID 38971758, 2024). "We propose that CCDC88C supports breast cancer metastasis possibly by promoting CEMIP transcription." (PMID 38971758, 2024). "We identified changes in transcriptional levels of CEMIP in breast cancer cells induced by CCDC88C that required c-JUN." (PMID 38971758, 2024). "The expression of CEMIP is significantly higher in breast cancer tissues compared to normal breast tissues, and its levels inversely correlate with both overall survival and post-progression survival of patients with breast cancer." (PMID 38838145, 2024). "CEMIP has been shown to be a critical pro-metastatic protein in several types of tumors, including breast cancer." (PMID 38838145, 2024). "For example, CEMIP enhanced the proliferative and migrative capabilities of breast cancer and prostate cancer cells." (PMID 39481283, 2024). "It has been shown that CEMIP expression in breast cancer is dependent on the AP‐1 binding site in the promoter region." (PMID 37313693, 2023). "In recent studies on breast cancer, it is found that REST directly binds to the RE1 site of CEMIP gene, inhibits CEMIP expression, and weakens the proliferative capacity of breast cancer cells." (PMID 37662915, 2023). "In the experiments on breast cancer brain metastasis, the overexpression of CEMIP promotes the proliferation of cerebral vascular epithelial cells." (PMID 37662915, 2023). "Another study reported that the inhibition of H3K27me3 demethylases suppressed migration and invasion in breast cancer cell lines by the inactivation of CEMIP (cell-migration-inducing hyaluronidase)." (PMID 36768182, 2023). "One of the up-regulated genes in the compartment B-to-A switch region was cell migration inducing hyaluronidase 1 (CEMIP), which has been reported to promote the proliferation and migration of breast cancer cells." (PMID 37381036, 2023). "The basic promoter activity of CEMIP is also regulated by DNA methylation and in human breast cancer hypomethylation correlates with high CEMIP expression." (PMID 36291875, 2022). "For example, CEMIP expression in breast cancer is between 2- and 8-fold higher than in normal breast tissue, depending on the molecular subtype." (PMID 36291875, 2022).
breast carcinoma (continued). "CEMIP knockdown in breast cancer cells results in reduced proliferation in vitro, and when CEMIP knockdown cells are injected into the mammary fat pads of female athymic nude mice, there is a significant decrease in tumor incidence and growth." (PMID 36291875, 2022). "The CRISPR-Cas9-mediated ablation of CEMIP in brain-tropic breast cancer cells has been shown to inhibit the formation of brain metastases following intra-cardiac injection." (PMID 36291875, 2022). "Recently, CEMIP was found to promote PKCα membrane transposition, enhancing its activity in breast cancer cells." (PMID 35013120, 2022). "We also found that CEMIP mRNA expression level was significantly higher in breast cancer tissues of different individual stage than in normal tissues." (PMID 35370456, 2022). "Overexpression of CEMIP has been previously reported in breast cancer patient samples and more aggressive breast cancer cell lines." (PMID 35177031, 2022). "In colorectal and breast cancer, CEMIP expression inversely correlates with E-cadherin expression and is found in the invasive edge of tumors." (PMID 36291875, 2022). "Hypermethylation of this region is seen in low expressing CEMIP breast cancer cell lines whereas hypomethylation is seen in high expressing CEMIP cell lines." (PMID 35177031, 2022). "Exosomes derived from brain tropic breast cancer cells are enriched with CEMIP, which promotes vascular co-option, and therefore, successful invasion and metastatic colonization of the brain." (PMID 34639239, 2021). "Then, the Breast Cancer Gene-Expression Miner v4.7 resource was employed to confirm the prognostic value of CEMIP, with which we further performed survival analysis in ER/PR-positive BC patients and ER/PR-negative BC patients." (PMID 34966410, 2021). "A recent study by Rodrigues and co-workers unraveled the role of exosomal cell migration-inducing and hyaluronan-binding protein (CEMIP) in brain metastization by breast cancer cells." (PMID 34639239, 2021). "Cell migration-inducing hyaluronidase 1 (CEMIP), a Wnt-related protein and also known as KIAA1199, is implicated in the process of metastatic colonization in a variety of malignant tumors, including breast cancer (BC), which is one of the most frequently diagnosed tumors in women worldwide." (PMID 34966410, 2021). "To investigate a possible link between CEMIP and BiP expression, we analyzed mRNA expression in 51 breast cancer cell lines characterized in the Cancer Cell Line Encyclopedia (Novartis/Broad, Nature 2012) using cBioPortal." (PMID 31303964, 2019). "This study identified for the first time a positive correlation between CEMIP and BiP expression in human breast cancer cell lines." (PMID 31303964, 2019). "Here we show that CEMIP mediates activation of the BiP promoter and upregulates BiP transcript and protein levels in breast cancer cell lines." (PMID 31303964, 2019). "Taken together, these results suggest that CEMIP upregulates BiP expression in breast cancer cell lines." (PMID 31303964, 2019). "Notably, KIAA1199 (CEMIP) has been increasingly implicated in malignant progression across multiple carcinomas, including breast cancer, where its overexpression mediates invasive phenotypes." (PMID 40646377, 2025). "Our data also suggest that the function of CCDC88C in breast cancer metastasis requires CEMIP." (PMID 38971758, 2024). "CEMIP, one of these overlapping genes, has been confirmed to confer breast cancer metastasis." (PMID 38971758, 2024). "CEMIP expression is very high in small EVs released by lung and breast brain metastases, although not in metastases located elsewhere or even in the primary lung or breast cancer cells." (PMID 35163368, 2022). "STAT3 was activated by CEMIP to facilitate for proliferation and migration of breast cancer." (PMID 35543351, 2022). "REST knockdown in breast cancer cells leads to significant upregulation of CEMIP and MMP24." (PMID 35177031, 2022).
breast carcinoma (continued). "Overexpression of CEMIP contributes to metastasis and invasion in RESTless breast cancer." (PMID 35177031, 2022). "Based on clinical studies showing that expression of CEMIP is inversely correlated with cancer survival rate in patients with breast cancer, colon cancer, and gastric cancer, CEMIP could positively affect cancer cell invasion through enhanced cell migration." (PMID 26009875, 2015). "The top four upregulated differentially expressed genes (DEGs), SAA2, UBE2C, CEMIP and ANXA8L1, have been associated with increased inflammation, cancer progression, metastatic potential and overall poor survival outcomes of various cancers including breast cancer." (PMID 39768151, 2024). "CEMIP, located on chromosome 15q25, serves as a downstream gene of c-JUN, and its transcription is reduced by knockdown of c-JUN in breast cancer cells." (PMID 38971758, 2024). "For example, CEMIP can activate the STAT3 signaling pathway in a BiP-dependent manner, thereby promoting the proliferation and migration of breast cancer cells." (PMID 36291875, 2022). "CEMIP and MMP24 have been previously shown to be upregulated in breast cancer patient samples and cell lines." (PMID 35177031, 2022). "Another protein carried by small EVs and released from brain metastatic lung and breast cancer cells is the cell migration-inducing and hyaluronan-binding protein (CEMIP or KIAA1199)." (PMID 35163368, 2022). "Future directions for determining the functional roles CEMIP and MMP24 play in breast cancer pathogenesis and metastasis will include invasion and migration assays in the presence and absence of REST, CEMIP and MMP24." (PMID 35177031, 2022). "The results of the group suggest that CEMIP can predict the progression of BCBM and patient survival and that targeting small EVs CEMIP holds promise as a potential means of preventing and treating breast cancer brain metastasis." (PMID 37091342, 2023). "However, additional studies are needed to determine the exact roles CEMIP and MMP24 overexpression play in breast cancer." (PMID 35177031, 2022). "Therefore, further studies are needed to clarify how CEMIP and MMP24 are regulated in breast cancer." (PMID 35177031, 2022). "In this study, breast cancer cells that form brain metastases in experimental mice produce exosomes containing CEMIP, in contrast to exosomes from related breast cancer cells that do not metastasize to the brain." (PMID 36291875, 2022). "The H3K4me3 modification was highly enriched in MDA-MB-231 cells, an aggressive human breast cancer cell line that expresses high levels of CEMIP, as compared to MCF-7 cells, which express lower levels of CEMIP, demonstrating a correlation between CEMIP expression and the level of the H3K4me3 mark." (PMID 26009875, 2015).
colorectal cancer (24 papers, 2012 to 2026). A primary or metastatic malignant neoplasm that affects the colon or rectum. "CEMIP is more than just a highly upregulated biomarker in CRC, as the enhanced expression of CEMIP has also been associated with poor prognosis in colorectal cancer patients and is an independent prognostic factor in this context." (PMID 36291875, 2022). "In BRAFV600E-mutated colorectal cancers, CEMIP expression is increased in a β-catenin-dependent manner, which contributes to acquired resistance to Mitogen-activated protein kinase kinase 1 (MEK1) inhibition." (PMID 36291875, 2022). "The nuclear localization of the CEMIP protein has also been suggested in colon cancer cell lines and has also been reported in samples from a subset of colorectal cancer patients, where nuclear localization has been associated with a reduced incidence of lung and liver metastases." (PMID 36291875, 2022). "Increased levels of endosomal CEMIP as a consequence of Wnt signaling have been implicated in mediating resistance to MEK inhibitors in BRAFV600E-mutated colorectal cancers, which is mediated by the binding of CEMIP to MEK1 and subsequent sustained ERK1/2 activation." (PMID 36291875, 2022). "Consistently, the expression of CEMIP in colorectal cancer cells is reduced by the dominant-negative form of TCF4 and increased by β-catenin-dependent transcription." (PMID 36291875, 2022). "Mechanistic studies in hepatocellular and colorectal cancer cells have shown that CEMIP knockdown leads to decreased levels of cyclin D1 and E1, hindering cell-cycle progression, increasing apoptosis, and attenuating tumor growth and metastasis." (PMID 36291875, 2022). "In colorectal cancer, hypoxia-mediated overexpression of CEMIP in submucosa epithelial cells leads to eventual enhanced cell migration status." (PMID 35687691, 2022). "In this review, we survey our current understanding of how CEMIP contributes to tumor growth and metastasis, focusing particularly on colorectal cancer, for which it serves as a promising biomarker." (PMID 36291875, 2022). "High CEMIP expression was related to poor prognosis of colon cancer and reduction of CEMIP repressed colorectal cancer invasion and metastasis." (PMID 35543351, 2022). "Studies showed that CEMIP was essential for maintaining cell metastasis and EMT in sorafenib-resistant hepatocellular carcinoma cells, and also demonstrated that CEMIP trigged acquired resistance to selumetinib in colorectal cancer cells." (PMID 35957875, 2022). "Here, we review our current understanding of how CEMIP is able to foster the process of tumor growth and metastasis, focusing particularly on colorectal cancer." (PMID 36291875, 2022). "Most significantly, it is increasingly recognized that CEMIP plays an important role in the genesis, progression, and metastasis of a growing number of cancer types, among which is colorectal cancer." (PMID 36291875, 2022). "In a study on colorectal cancer, CEMIP increased the phosphorylation of PP2A." (PMID 37662915, 2023). "The therapeutic delivery of CEMIP-regulating miRNAs may also have utility, as the enforced expression of miR-216a downregulates CEMIP in colorectal cancer cells and as a result suppresses tumor invasion and metastasis." (PMID 36291875, 2022). "Importantly, the reciprocal regulation of CEMIP and Wnt/β-catenin signaling enhances the glutamine metabolic reprogramming of colorectal cancer cells, which fosters metastasis." (PMID 36291875, 2022). "Other researches showed that the cell proliferation and mobility of colorectal cancer cells were inhibited by knocking down the expression of CEMIP in vitro, and the EMT process of colorectal cancer cells is suppressed by shRNA-CEMIP via inactivation of the Wnt/β-catenin/Snail pathway." (PMID 33194340, 2020).
colorectal cancer (continued). "Moreover, the physical association between CEMIP and the protein phosphatase 2A (PP2A) increases the phosphatase activity of PP2A in colorectal cancer cells, resulting in decreased phosphorylation of the microtubule-destabilizing protein stathmin, which enhances cell motility." (PMID 36291875, 2022). "A distinct scaffolding function was observed in CEMIP, mediating GRAF1 and MIB1 coordination, thereby instigating metastatic events in colorectal cancer through CDC42/MAPK pathway activation." (PMID 39624211, 2024). "In the context of colorectal cancer (CRC), it is notable that CEMIP has been identified in several screens as one of the most highly upregulated genes in tumors compared with normal tissues." (PMID 36291875, 2022). "In addition, they also demonstrated that the combination of CEMIP inhibition and immune checkpoint blockade (ICB) impeded tumor growth and enhanced therapeutic efficacy in colorectal cancer." (PMID 37662915, 2023).